MIR660 (microRNA 660)
Synonyms: hsa-mir-660; MIRN660; mir-660
Gene: MicroRNA gene on chromosome X (50,013,241 to 50,013,337, forward strand). Ensembl gene ENSG00000207970.
Gene Ontology:
Biological process: miRNA-mediated post-transcriptional gene silencing
Homologues: Orthologues: chimpanzee ptr-mir-660 (100% identical), macaque mml-mir-660 (99% identical). Paralogues in human: MIR188 (64% identical), MIR532 (52% identical).